KRASP1 (KRas proto-oncogene, GTPase pseudogene 1)
Synonyms: formerly KRAS1P
Gene: Processed pseudogene on chromosome 6 (54,770,583 to 54,771,134, forward strand). Ensembl gene ENSG00000220635.
Diseases named in the same sentence as KRASP1 in open-access papers:
KRASP1 is named in the same sentence as 4 diseases in open-access papers, as found by Europe PMC text mining. Sharing a sentence is not in itself a finding about the gene and the disease. The quoted sentences say what the papers report.
HIV-1 infection (2 papers, 2015 to 2024). The type species of lentivirus and the etiologic agent of acquired immunodeficiency syndrome (AIDS). "The GAS5 family, KRASP1, lincRNA-p21 and LUST lncRNAs are responsible for reduced growth arrest and apoptosis, and increased cell proliferation, which positively impacts HIV-1 infection and replication." (PMID 25728138, 2015).
breast carcinoma (1 paper, 2015). "It is worth noting that PTENP1 and KRASP1, the two initial examples of pseudogene ceRNAs, are present (though at low levels) in the breast cancer samples we study here." (PMID 25765044, 2015).
cancer (5 papers, 2019 to 2025). A tumor composed of atypical neoplastic, often pleomorphic cells that invade other tissues. "Parallel to PTENP1, other pseudogenes like KRASP1 and BRAFP1 have been implicated in cancer pathogenesis through similar ceRNA mechanisms, with KRASP1 sponging miR‐143 and let‐7 family to protect KRAS mRNA and BRAFP1 enhancing oncogenic signaling by sequestering microRNAs that target BRAF." (PMID 41473691, 2025). "The pervasive dysregulation of pseudogenes across cancer types—with some functioning as tumor suppressors (e.g., PTENP1) and others as oncogenic drivers (e.g., KRASP1, BRAFP1)—highlights their importance as a novel class of cancer genes." (PMID 41473691, 2025). "Some cancer related pseudogenes could regulate the expression of their corresponding coding genes such as KRAS and KRASP1, KRAS, and KRASP1 by sequestering the interacting miRNAs." (PMID 31146489, 2019).
KRASP1 also shares sentences with these, for which no sentence is quoted: tumor (1 paper).